UCA1 (urothelial cancer associated 1)
Diseases named in the same sentence as UCA1 in open-access papers (continued):
Sharing a sentence is not in itself a finding about the gene and the disease.
bladder cancer (continued). "Hence, the UCA1/Wnt6 pathway may be able to prevent bladder cancer." (PMID 37405480, 2023). "In other words, UCA1 affects the expression of pre-rRNA and GTPase activity by regulating IMPDH1 and IMPDH2, thus promoting the malignant behavior of bladder cancer." (PMID 37215997, 2023). "In summary, we have clarified the molecular mechanism by which UCA1 controls IMPDH1/2 expression via TWIST1 to change metabolite levels and promotes guanine nucleotide de novo anabolic reprogramming and bladder cancer progression." (PMID 37215997, 2023). "UCA1 has been demonstrated to increase EMT by zinc finger E‐box binding homeobox 1 and 2 (ZEB1 and ZEB2) upregulation in bladder cancer cells." (PMID 36685879, 2022). "For example, lncRNA UCA1 could activate the mTOR pathway, mediate the regulation of urothelial cancer associated 1 (UCA1) to HK2 through activation of signal transducer and activator of transcription 3 (STAT3), then promote glycolysis, exert promotion effects on tumorigenesis in bladder cancer." (PMID 36072431, 2022). "UCA1, hnRNP I/L, and GPT2 functionally facilitate tumor growth and are involved in glutamine-driven anaplerosis in bladder cancer cells." (PMID 36499136, 2022). "In line with miR-145 sponging by UCA1, over-expression of it leads to the upregulation of FSCN1 and ZEB1/ZEB2 factors promoting bladder cancer development by induction of EMT process and increasing the invasiveness potential." (PMID 35447891, 2022). "Moreover, the expression of UCA1 may be affected by bladder cancer cells." (PMID 35289508, 2022). "UCA1 promotes glycolysis and upregulates hexokinase 2 expression via the mTOR-STAT3/miR-143 pathway in bladder cancer cells." (PMID 33777227, 2021). "UCA1 can also inhibit the level of cAMP response element-binding (CREB) protein, and regulate the cell cycle of bladder cancer cells via the PI3K-dependent pathway." (PMID 33777227, 2021). "In bladder cancer, several lncRNA/miRNA axes have acted as regulators of cancer metastasis, including lncRNA H19/miR-29b, lncRNA XIST/miR-124 and lncRNA UCA1/miR-196a." (PMID 33902589, 2021). "UCA1/miRNA204-5p/cAMP responsive element binding protein-1 (CREB1) axis, UCA1/miRNA-143/Fos-like antigen 2 (FOSL2) axis, and UCA1/miRNA-196a-5p/CREB axis were involved in enhancing the chemoresistance of colorectal, ovarian, and bladder cancers." (PMID 34544452, 2021). "UCA1 regulates the expression of GLS2 by interfering with miR-16, and blocked ROS formation in bladder cancer." (PMID 33610185, 2021). "In bladder cancer and SLE, UCA1 is highly expressed and promotes cell proliferation by mediating the PI3K/AKT signaling pathway." (PMID 33777227, 2021). "UCA1 has a further oncogenic function by enhancing mTOR/STAT3/HK2 signaling pathway, which promotes Warburg effect of bladder cancer." (PMID 34422802, 2021). "Further study revealed that UCA1 functioned as a miR-16 sponge to reduce ROS production and induce GLS2 expression, leading to increased glutaminolysis in bladder cancer cells." (PMID 35006436, 2020). "Recently, more and more studies have suggested that lncRNAs, such as UCA-1, MALAT1, PANDAR and so on, play key roles in development and progression of bladder cancer." (PMID 31844718, 2019). "Taken together, our study confirmed that BMP9 can increase the expression of UCA1 through phosphorylated AKT, which promotes the proliferation and migration of bladder cancer cells." (PMID 29642505, 2018). "To date, many aberrantly expressed lncRNAs have been identified in bladder cancer, including upregulated lncRNAs, H19, MALAT1, SNHG16, TUG1, UCA1, TINCR and Linc-UBC1; and downregulated lncRNAs, BANCR and MEG3." (PMID 29719633, 2018). "This study showed that H19, SNHG16, UCA1, PTENP1 and MEG3 were aberrantly expressed in bladder cancer tissues." (PMID 30285771, 2018). "UCA1 can act as a competing endogenous RNA (ceRNA) and contributes to ARL2-induced mitochondrial activity by inhibiting miR-195-5p in bladder cancer." (PMID 30134946, 2018).
bladder cancer (continued). "For instance, UCA1, which promotes EMT in bladder cancer cells, was found to be induced in bladder cancer cells under hypoxic conditions by the direct binding of HIF-1α to its promoter." (PMID 28430163, 2017). "Recently, it was shown that UCA1 transcription is induced by HIF-1α, to enhance hypoxic proliferation, migration and invasion of bladder cancer cells." (PMID 28715488, 2017). "Like UCA1, another lncRNA Taurine upregulated gene 1 (TUG1), also promotes EMT and invasion in bladder cancer through acting as a ceRNA for miR-145 and liberation of expression of the miR-145 target ZEB2." (PMID 28430163, 2017). "Furthermore, some studies have shown that UCA1 was related to drug resistance in some malignancies, including ovarian cancer, bladder cancer and EGFR-mutant NSCLC, suggesting that UCA1 could be applied as a biomarker for monitoring the efficacy of chemotherapy." (PMID 27517147, 2016). "Numerous studies have shown that UCA1 made effects as an oncogenic lncRNA by inhibiting known tumor suppressors, such as p27 and miR-143 in breast cancer and BRG1 in bladder cancer." (PMID 27517147, 2016). "The lncRNAs H19, UCA1, CUDR, HIF1A-AS are reliable biomarkers and potential therapeutic targets for bladder cancer." (PMID 26082843, 2015). "Ectopic expression of UCA1 lncRNA in BLS-211, a bladder cancer cell line, significantly enhanced tumorigenicity and invasive potential of cells." (PMID 24993775, 2014). "Certain recent studies have reported that several lncRNAs, including UCA1, MALAT-1 and ncRAN, show marked potential in the field of bladder cancer progression." (PMID 24944692, 2014). "In bladder carcinoma cells, CREB level was significantly down-regulated after knocking down of lncRNA UCA1." (PMID 24289115, 2013). "Of note, H19, UCA1 and SNHG15 have been recently studied in bladder cancer." (PMID 40461454, 2025). "A panel of 96 target lncRNAs was used as a probe, some of which have been previously demonstrated to be involved in the development of bladder cancer or other tumors (UCA1, MALAT1, H19, and HOTAIR), while others have not yet been characterized." (PMID 38846969, 2024). "Moreover, a three exosomal lncRNA panel (RMRP, UCA1 and MALAT1) are elevated in bladder cancer, and is correlated with the tumor stage of bladder cancer." (PMID 37805491, 2023). "Hence, lncRNAs, such as MEG3, UCA1, and ADAMTS9-AS1, have been shown to regulate autophagy in bladder cancer; however, further research is crucial to elucidate their effects and mechanism in bladder carcinogenesis." (PMID 36899946, 2023). "UCA1 upregulates glutamate pyruvate transaminase 2 (GPT2) expression through interaction with heterogeneous nuclear ribonucleoprotein I/L, and promotes glutamine driven bladder cancer reperfusion." (PMID 37215997, 2023). "A study has reported that UCA1 impairs the binding of brahma-related gene 1 (BRG1) to the p21 promoter and the chromatin remodeling activity of BRG1 to accelerate the proliferation of bladder cancer cells." (PMID 33777227, 2021). "Additionally, UCA1 is modulated by upstream molecules, such as bone morphogenetic protein 9 (BMP9), which then promotes tumor progression of bladder cancer." (PMID 34422802, 2021). "Notably, the mRNA level of UCA1 and GLS2 are positively correlated, and the expression of GLS2 is negatively correlated to the miR-16 in bladder cancer." (PMID 33849550, 2021). "UCA1 expression increased in hypoxic exosomes from bladder cells compared to non-hypoxic exosomes and serum-derived exosomes from bladder cancer patients." (PMID 33050642, 2020). "For example, higher urinary exosomal LNMAT2, higher urinary and serum exosomal circPRMT5, higher serum exosomal UCA1, the PCAT-1, UBC1, SNHG16 panel, higher plasma exosomal H19 and lower plasma exosomal PTENP1 were more frequently observed in bladder cancer patients than in healthy controls." (PMID 32517366, 2020).
bladder cancer (continued). "Among all these lncRNAs, UCA1-201 transcript levels had the best performance to discriminate between bladder cancer from normal/nonmalignant disease samples, and thus indicating its potential use as a prognostic biomarker in BC." (PMID 35582278, 2019). "Previous studies have identified that lncRNAs like LINC00460, UCA1, LINC00958, LINC01296, SNH12, and DUXAP8 are implicated in bladder cancer, but did not examine the entire landscape of lncRNA transcripts." (PMID 31810243, 2019). "Moreover, in bladder cancer cells, by acting as a miR-16 sponge and upregulating the expression of miR-16 targeting GLS2, UCA1 contributes to glutamine metabolism and represses ROS formation in bladder cancer." (PMID 30134946, 2018). "As indicated by recent studies, UCA1 activates mTOR by upregulating HK2 and increases glycolysis through both the activation of STAT3 and the repression of miR-143, thereby revealing a novel glucose metabolism regulatory pathway, UCA1-mTOR-STAT3/miR-143/HK2, in bladder cancer cells." (PMID 30134946, 2018). "Moreover, expression of lncRNA UCA1, miR-196a-5p and p-CREB was positively correlated in bladder cancer tissues." (PMID 28969100, 2017). "Also in bladder cancer several oncogenic and tumor suppressive lncRNAs have been identified, such as H19, MALAT1, MEG3, SNHG16, TUG1 and UCA1." (PMID 28415801, 2017). "The positive and negative predictive values of the UCA1 test were lower than previously reported (64.5 and 75.6% respectively), despite a relatively high prevalence of bladder cancer in our patients population." (PMID 26191476, 2015). "UCA1 bound BRG1 and antagonized its suppressive effects in bladder cancer cells." (PMID 24993775, 2014). "We identified 8 lncRNAs of high level (LINC00221, UCA1, ZFHX4-AS1, LINC00284, LOC283731, LINC00698, CNTFR-AS1, and LOC284379) and 4 lncRNAs of low level (LINC00390, SSTR5-AS1, HECTD2-AS1, and LOC400696) were significantly related to the progression of muscle-invasive bladder cancer." (PMID 27863388, 2016). "Notably, analysis of UCA1 and BRG1 expression in three bladder cancer cell lines (5637, T24 and EJ cells) revealed a relationship between BRG1 and UCA1 expression, suggesting that these two molecules may be functionally related." (PMID 24993775, 2014). "UCA1 modulates behavior of bladder cancer cell lines, but there are no data on its function in primary cells; our results suggest that UCA1 may be involved in premature senescence." (PMID 24876127, 2014). "UCA1 is highly expressed in embryonic tissues, bladder cancers and other cancers, but not in adult tissues or adjacent non-neoplastic tissues, which indicates that UCA1 may be involved in both embryonic development and carcinogenesis." (PMID 24006935, 2013). "Moreover, lncRNA UCA1 contributes to progression of hepatocellular carcinoma through inhibition of miR-216b and activation of FGFR1/ERK signaling pathway and is upregulated in breast cancer, colorectal cancer, esophageal squamous cell carcinoma and bladder carcinoma." (PMID 28427159, 2017). "There have been several reports that UCA1 affected AKT expression and the activity of the PI3K-Akt-mTOR signaling pathway in the progression of bladder carcinoma cells, prostate cancer, breast cancer and non-small cell lung cancer, but similar studies of gastric cancer have not been reported." (PMID 29212166, 2017).
gastric cancer (121 papers, 2014 to 2025). A primary or metastatic malignant neoplasm involving the stomach. "Long non-coding RNA UCA1 (lncRNA-UCA1) has emerged as a promising biomarker for early detection and prognostic prediction in gastric cancer, with elevated levels linked to poorer OS and disease-free survival." (PMID 40071088, 2025). "As an oncogene, LncRNA urothelial carcinoma‐associated 1 (UCA1) was found to be often highly expressed in gastric cancer." (PMID 35592755, 2022). "A similar phenomenon occurs in gastric cancer with lncRNA urothelial cancer-associated 1 (UCA1) which binds to EZH2 and induces the down-regulation of tumor-suppressor factors including p21 and Sprouty RTK signaling antagonist 1 (SPRY1)." (PMID 35236381, 2022). "The regulatory roles of lncRNA UCA1 are implicated in esophageal cancer, gastric cancer, pancreatic cancer, hepatobiliary cancer, and colorectal cancer, where they shared similar molecular mechanisms in regulating cancer phenotypes and chemoresistance." (PMID 33936199, 2021). "In this study, we aim to investigate the role of UCA1 in the cisplatin treatment of gastric cancer and its underlying mechanism." (PMID 32328192, 2020). "In gastric cancer, UCA1 (Urothelial Cancer-Associated 1) promotes PD-L1 expression by repressing miR-26a/b, miR-193a, and miR-214, which contributes to immune escape of gastric cancer cells." (PMID 33194608, 2020). "Urothelial carcinoma associated 1 (UCA1) is an independent prognostic biomarker, which contributed to adriamycin resistance in gastric cancer." (PMID 30761271, 2019). "LncRNA urothelial carcinoma associated 1 (UCA1) mediates resistance to doxorubicin treatment in gastric cancer." (PMID 29967761, 2018). "In this study, we found that UCA1 was aberrantly elevated in gastric cancer tissues, and was significantly associated with lymph node metastasis and TNM stage." (PMID 30464170, 2018). "In this study, we mainly focus on the influence of UCA1 on GC cells and the underlying mechanism of UCA1 in gastric cancer." (PMID 28569779, 2017). "In the present study, we found that UCA1 was aberrantly upregulated in gastric cancer tissues and gastric cancer cell lines, and was associated with TNM stage and metastasis." (PMID 29212166, 2017). "Aberrant expression of UCA1 (urothelial carcinoma-associated 1) and three other lncRNAs were found in the co-expression network with 26 mRNAs involved in the progression of gastric cancer." (PMID 26378581, 2015). "Another explored Urothelial Cancer-Associated 1 (UCA1) in gastric cancer, demonstrating that UCA1 interacts with miR-145 and MYO6, forming a regulatory axis that affects cancer cell proliferation and apoptosis, suggesting new therapeutic approaches targeting regulatory axis." (PMID 40861865, 2025). "Another study with gastric cancer cells showed that lncRNA urothelial carcinoma associated 1 (UCA1) upregulates PD-L1 expression through sponging miR-214 and 193a, which usually target PD-L1 3′UTR, also contributing to cancer cell migration, invasion and drug resistance in gastric cancer." (PMID 37835376, 2023). "In addition to that, UCA1 is also an oncogene in gastric cancer that causes enhanced proliferation and migration and reduced apoptosis while depletion of UCA1 restrains tumor progression in vitro and in vivo." (PMID 34053467, 2021). "UCA1 has also been reported to be associated with drug resistance in breast and gastric cancer." (PMID 29416703, 2018). "In gastric cancer patients, plasma levels of urothelial cancer associated 1 (UCA1/CUDR), long stress-induced non-coding transcript 5 (LSINCT-5), phosphatase and tensin homolog pseudogene 1 (PTENP1), and cytoskeleton regulator RNA (CYTOR/LINC00152) were higher than in healthy individuals." (PMID 29614786, 2018).
gastric cancer (continued). "For example, lncRNA urothelial cancer associated 1 (UCA1) is upregulated in gastric cancer tissues, and promotes the growth and cell cycle process through binding to enhancer of zeste 2 polycomb repressive complex 2 subunit (EZH2) and facilitating cyclin D1 expression in gastric cancer cells." (PMID 29773901, 2018). "Urothelial carcinoma-associated 1 (UCA1) is a lncRNA with three exons, and several recent studies have demonstrated oncogenic functions of UCA1 in various types of cancer, such as breast, bladder, colorectal, and gastric cancer." (PMID 30377411, 2018). "Urothelial carcinoma-associated-1(UCA1) is highly expressed in the plasma of Gastric Cancer (GC) patients, and can be a promising noninvasive diagnostic biomarker for GC." (PMID 27527868, 2016). "MYO6 is highly expressed in prostate cancer, ovarian cancer, gastric cancer and oral squamous cell carcinoma and can promote proliferation and migration through the lncRNA UCA1/miR-143/MYO6 axis." (PMID 41262242, 2025). "Many oncogenic lncRNAs, including nuclear paraspeckle assembly transcript 1 (NEAT1), MALAT1, UCA1, and prostate cancer-associated transcript 1 (PCAT-1), as well as some tumor suppressor lncRNAs, have been shown to play a role in gastric cancer chemoresistance." (PMID 38294554, 2024). "The non-coding RNA UCA1 plays a regulatory role in the stability of GRK2 protein in gastric cancer (GC) cells." (PMID 39130630, 2024). "Emerging evidence has indicated that UCA1 is frequently found dysregulated in several tumors, such as bladder, colorectal, and gastric cancers." (PMID 38534790, 2024). "A study conducted on gastric cancer cells indicates that increased UCA1 expression is correlated with poor prognosis and reduced survival rates." (PMID 39690423, 2024). "Most literatures had reported that the expression level of UCA1 in the majority digestive tract tumors such as gastric cancer, hepatocellular carcinoma and colon cancer was higher than that in adjacent tissues." (PMID 37564930, 2023). "Circulating UCA1 levels showed potential value in diagnosis of early-stage colorectal cancer and in predicting the prognosis of patients with gastric cancer." (PMID 37564930, 2023). "The expression of UCA1 was increased in tissues or cell lines of gastrointestinal cancers, such as gastric cancer, colorectal cancer, hepatocellular carcinoma, which promoted cell proliferation, metastasis, and drug resistance by interacting with miRNAs." (PMID 37564930, 2023). "The abnormal expression of UCA1 was found to suppress cell apoptosis and promote cell proliferation in gastric cancer." (PMID 35592755, 2022). "The LncRNA UCA1, which is upregulated in gastric cancers, recruits EZH2 (enhancer of zeste homolog 2) to the promoters of the genes that encode p27 (CDKN1B) and the sprouty RTK signaling antagonist 1 (SPRY1) to mediate the repressive H3K27me3-trimethylation." (PMID 36010595, 2022). "For example, lncRNA-CTS can up-regulate ZEB2 expression by adsorbing miR-505 to facilitate CC cell migration, invasion and EMT; lncRNA UCA1 can regulate the miR-203/ZEB2 axis to facilitate gastric cancer cell migration and invasion." (PMID 35435130, 2022). "The lncRNA UCA1 is a prognostic factor in gastric cancer with its upregulation being correlated to unfavorable prognosis." (PMID 35236381, 2022). "The results of our study demonstrated that the five-lncRNAs PART1, UCA1, DIRC3, HOTAIR, and HOXA11AS require more investigation to be confirmed as diagnostic biomarkers in gastric cancer." (PMID 35949302, 2022). "For example, the expression level of serum lncRNA UCA1 is very important for the early diagnosis of gastric cancer." (PMID 35308365, 2022). "LncRNA UCA1 promoted proliferation, migration, and immune escape and inhibited cell apoptosis in gastric cancer." (PMID 34012919, 2021).